IL2 (interleukin 2)
Diseases named in the same sentence as IL2 in open-access papers (continued):
Sharing a sentence is not in itself a finding about the gene and the disease.
leukemia (continued). "We also found that T-ALL cells can increase the expression of IL-4 after treatment with IL-2 and that IL-2 can activate the PKC and GRK2 signaling pathways to induce CCR9 internalization, thereby reducing leukemia cell infiltration and metastasis." (PMID 26879872, 2016). "The production of IL-2, TNF-a and IFN-r secreted by PD1hiTIM3+ cells were reduced in leukemia patients." (PMID 27447564, 2016). "Gallein, a small molecule inhibitor of Gβγ, increased levels of T cell receptor (TCR)-stimulated IL-2 mRNA in primary human naïve and memory CD4+ T helper cells and in Jurkat human CD4+ leukemia T cells." (PMID 25629163, 2015). "Further, picomolar concentrations of IL-2 are able to selectively impact CIML NK cells in vitro via enhanced costimulation of IFN-γ, cytotoxicity against leukemia targets, and proliferation." (PMID 25054077, 2014). "Interestingly, after a single round of expansion with IL-2, WT and MCJ KO CD8 CAR-T cells equally prolonged the survival of mice with leukemia." (PMID 38789421, 2024). "Therefore, we investigated the effect of IL-2/JES6 immunocomplexes which were previously considered tolerogenic, in a BCL1 leukemia model." (PMID 36705564, 2023). "For example, TIM-3+PD-1+CD8+ T cells in mice with advanced AML exhibited severe exhausted phenotype as defined by failure to produce IL-2, tumor necrosis factor and interferon-γ, and combined targeting of TIM-3 and PD-1 pathways was more effective in controlling the leukemia burden." (PMID 35494006, 2022). "CIK cells expanded at rest, during exercise (at 60% and 80% VO2max) or after (1h post) were equally capable of killing leukemia, lymphoma, and multiple myeloma target cells with and without cytokine (IL-2) and antibody (OKT3) priming in vitro." (PMID 36189306, 2022). "These experiments showed that TE9-28ζ and CD19-28ζ CAR-T cells had sustained capacity to produce IL-2 in response to a fourth rechallenge with B7-H3-positive leukemia cells, while TC6 and BH6 CAR-T cells had become non-responsive by the fourth stimulation." (PMID 36159778, 2022). "Interestingly, when IL-2 + IL-15 and ZOL are administered to γδ T cells isolated from patients with leukemia, during 14 days of culture, they assume different phenotypic states." (PMID 34630403, 2021). "For example, as IL-2 can stimulate NK cells against ovarian cancer in a murine model, further evaluation of IL-2 and other therapies in the SCID pig may further delineate the clinical relevance of NK cells in anti-leukemia and anti-lymphoma immune responses." (PMID 31293961, 2019). "In aggregate, these results proved that CSPG4-CAR T cells evince an antigen-specific secretion pattern of Th1 cytokines in response to KOPN8 leukemia cells, without IL-2 and IL-4 production." (PMID 31195686, 2019). "IL-2 is required for T-cell activation, differentiation, and survival but can also be favorable as IL-2 selectively can restore the immunosuppressive function of FoxP3 Tregs without activation of T-cells or abrogation of anti-leukemia effects." (PMID 31105702, 2019). "Strikingly, while antigen-specific IL-2 production was detected following co-culture with A375M cells, hardly any IL-2 secretion by CSPG4-CAR T cells was observed upon stimulation with KOPN8 leukemia cells." (PMID 31195686, 2019). "Cytokines activating STAT5 additionally such as IL-2, IL-3, IL-7, GM-CSF and many others could enhance the effect of BCR-ABL and promote leukemia induction and maintenance." (PMID 28753604, 2017). "Interleukin-2 treatment after DLI in patients with relapsed leukemia after allo HSCT did not provide beneficial outcome, and increased the occurrence of GVHD." (PMID 28574833, 2017). "Here, we lentiviral-transduced the same CD19 CAR into Dynabead T cells, OKT3-28BB-86BBL RNA-T cells, and OKT3/IL-2 T cells and tested their anti-leukemia activity in the Nalm6 model, and the OKT3/IL-2 T cells were still inferior to the CD3/CD28 Dynabead T cells in controlling leukemia." (PMID 28523432, 2017).
leukemia (continued). "As mAb 4713 was not cytotoxic to NK lymphoma cell lines that depend on supplemental IL-2 for culture maintenance, we conclude that mAb 4713 has cytolytic activity only for lymphoma/leukemia cells that proliferate without exogenous IL-2." (PMID 27028595, 2016). "Quantitative measurement of the serum cytokines in mice after the induction of leukemia (WEHI-3) revealed the IL-10 level at 156.30±4.10 pg/mL, whereas the levels of IFN-γ, TNF-α, IL-12β, and IL-2 were 52.63±5.03, 42.63±3.77, 185.40±15.24, and 14.81±0.74 pg/mL, respectively." (PMID 26752299, 2016). "However, the addition of UO126 or/and LY294002 to the treatment reduced posterior leukemia targeting to basal (20–30%) levels; this was also the case for the more efficient (over 80% killing) combination of HMB-PP with IL-2." (PMID 19479075, 2009). "In addition, when over-expressed in the Jurkat T leukemia cell line, both PTP inhibit TCR-induced activation of the IL-2 promoter, an effect that requires an intact FERM domain necessary for translocation of these PTP to the plasma membrane." (PMID 19107198, 2008). "This discordant regulation between NKp30 and NKp46 by IL-2 deprivation is compatible with a recent study on the sustained expression of NKp46 but the downregulation of other activating receptors, such as NKp30, NKG2D, and NKp44, in tumor-infiltrating NK cells in diverse leukemia and tumors." (PMID 38698855, 2024). "Taken together, our data demonstrate that Hsp90 inhibition effectively reduces the cell viability and phosphorylation of STAT3 mutated primary LGL-leukemia cells even in absence of cytokine stimulation and its effect is further increased when JAK/STAT signaling is activated with IL2 and IL15." (PMID 29228628, 2017). "In lymphocytic leukemia, a hematologic tumor highly resistant to activated Vγ9Vδ2 T cells, IL-2 or IL-15, and TCR stimulation upregulates the expression of NK receptors NKp44, NKp46, and NKp30 on Vδ1+ T cells, allowing their acquisition of cytotoxicity against leukemia cells." (PMID 28713381, 2017). "Thus, AG-490 suppresses several signaling pathways, including IL-2-mediated signaling, which is upstream of JAK3 and STAT5A and B. Generally, AG-490 can be used to control the abnormal constitutive activation of JAK2 in leukemia cell lines." (PMID 24170986, 2013). "Indeed, co-culture withM.bovis BCG and IL-2 did not enhance the naturalcytotoxicity properties of human NK cells against the K562 leukaemia line althoughpromoting the production of IFN-γ." (PMID 23874793, 2013). "In just 3 hours, more than 80% of leukemia cells were killed by the γδ T-cells that had been stimulated with a combination of HMB-PP with IL-2 (compared to less than 20% by non-activated γδ T-cells), and such a regimen was at least as effective as saturating αCD3 plus IL-2." (PMID 19479075, 2009). "Hence, the absent IL-2 production by CSPG4-CAR T cells in response to leukemia cells might be beneficial to prevent a surge of regulatory T cells." (PMID 31195686, 2019). "Co-culture with IFN-γ-activated AML blasts resulted into an increase of FoxP3-expressing bona fide Treg cells, when compared with cultures maintained in the absence of leukemia blasts or with those nurtured with a polyclonal stimulus, such as PHA, and IL-2, a Treg growth factor." (PMID 24903009, 2014). "Four weeks after tumor injection, mice that had received HMB-PP plus IL-2-treated (activated and expanded over 12 days) γδ PBL showed significantly reduced tumor load (derived from Molt-4 leukemia cells) compared to control mice that did not receive γδ T-cells." (PMID 19479075, 2009).
lung carcinoma (111 papers, 1994 to 2025). "MART-1scTCR-IL-2 has not been tested in a MART-1-positive tumor model but showed partial antitumor efficacy in a lung cancer model tumor in which the increased half-life of IL-2 was propose as a supporting factor underlying efficacy." (PMID 39204319, 2024). "IL-2 and IL-1b demonstrated significant associations with lung cancer risk as well, with odds ratios of 2.16 (95% CI: 1.20–4.91, p = 0.009) and 1.88 (95% CI: 1.09–3.54, p = 0.030), respectively, for patients with levels above 17 pg/mL and 22 pg/mL." (PMID 37373957, 2023). "Baseline IL-1β and IL-2 levels in peripheral blood were associated with the occurrence of irAEs in lung cancer patients." (PMID 36091125, 2022). "Regular smoking, which is a predisposing factor for oral and lung cancer, correlated with higher levels of the proinflammatory cytokine IL-2 and with a higher microbial prevalence of Proteobacteria, Firmicutes, Bacteroidetes, Fusobacteria and Actinobacteria." (PMID 33153049, 2020). "In patients with lung cancer, the presence of tumor cells may lead to persistent activation of immune cells, thereby releasing more IL-2, which in turn causes an increase in sCD25 levels." (PMID 41312053, 2025). "In lung cancer tissues, low expression of IL2 was associated with poor prognosis." (PMID 36707691, 2023). "However, in gastric and lung cancer patients increased IL-2 levels were associated with advanced cancer stages." (PMID 32298379, 2020). "This suggests that the increased concentration of IL-2 in plasma from lung cancer patients may be one of the underlying reasons for the generation of PD-1+ NK cells in blood." (PMID 32788875, 2020). "CD4+ T cells activated using anti-CD3, followed by liposomal IL-2 administration, achieved tumor remissions and extended disease-free survival in mice with MC-38 colon adenocarcinoma, 3LL lung carcinoma, or 38C13 lymphoma." (PMID 40143046, 2025). "For example, aerosolized liposomal IL-2 formulations have been evaluated for their potential in treating pulmonary metastases and primary lung cancers, showing stability during nebulization and distribution throughout the lungs." (PMID 40143046, 2025). "The overexpression of IRF1 significantly inhibit the proliferation, invasion and migration of A549 lung cancer cells; and IL-2 augment the function of IRF1 on A549 lung cancer cells." (PMID 38915471, 2024). "The aim of this work is to examine that the Lung Cancer detection and treatment by introducing IL2 and anti-PD-L1 inhibitor for low immune individuals." (PMID 38483931, 2024). "Simulations are conducted to observe the symptomatic and asymptomatic effects of Lung Cancer disease to verify the relationship of IL2, anti-PD-L1 inhibitor and immune system." (PMID 38483931, 2024). "IRF1 and IL2 have a synergistic impact that inhibits the proliferation, migration, and invasion of A549 lung cancer cells, as demonstrated by both in vitro and in vivo tests." (PMID 38915471, 2024). "To this end, we cultured fresh PBMCs from lung cancer patients and controls with 5 μg/ml Con A and 50ng/ml IL-2 for 3 days." (PMID 37580655, 2023). "Myricetin restored the survival, proliferation, CD69 expression, and interleukin-2 (IL-2) secretion of Jurkat-PD-1 T cells suppressed by IFN-γ-treated lung cancer cells." (PMID 37764304, 2023). "Recently study identified that IL-2 can reverse CD8+ T cells with the exhaustion phenotype in the MPE of lung cancer." (PMID 36776832, 2023). "The ROC plot analysis revealed that IL-1b, IL-2, IL-6, IL-10, IL-12p70, and TNF-alpha had a significant association with lung cancer, although with relatively low discriminative performance." (PMID 37373957, 2023). "The role of IL-2 activation in restoring lymphocyte immunocompetence against lung cancer has also been demonstrated." (PMID 36874011, 2023). "A fluorinated IL-2, N-(4-[18F]fluorobenzoyl)-IL-2 (18F-FB-IL-2) has been used to detect activated T cells in the TME of a lung cancer model to monitor cancer therapy." (PMID 35223381, 2022).
lung carcinoma (continued). "Interleukin-2 activated pre-treated TALL-104 was co-cultured with the lung cancer cells A549 at a 2:1 effector-to-target (E:T) cell ratio for 24 h." (PMID 36497434, 2022). "More recently, N-(4-[18F]fluorobenzoyl)-IL-2 (18F-FB-IL-2) has been used to detect activated T cells in the TME of a lung cancer model." (PMID 33391977, 2021). "In a Phase I/II trial of breast and lung cancer, infusions of ex vivo IL-2‒activated NK cells were compared to injection of a bolus of IL-2." (PMID 32751977, 2020). "According to database analysis, we found that expression of NIK correlated significantly and positively with IL-2 or MMP9 expression in lung cancer patients." (PMID 33198776, 2020). "A recent study also showed that a manmade immunocytokine, 2aG4-IL2, which genetically links IL-2 to 2aG4, blocks PS induced immunosuppression in lung cancer." (PMID 32802188, 2020). "F16-IL2 (TELEUKIN®), an IL-2 coupled antibody-cytokine fusion protein is the most advanced candidate with two clinical trials in solid tumours, such as breast and lung cancer (NCT01131364, NCT01134250)." (PMID 32481570, 2020). "A combined treatment in a xenograft lung cancer model showed identical effects in immunodeficient mice bearing human lung cancer after adoptive transfer of TKD/IL-2-activated human effector cells and a human PD-1 antibody." (PMID 30967859, 2019). "IL-2 was proven to be effective to reverse CD8+ T cell exhaustion in malignant pleural effusion of lung cancer." (PMID 31632413, 2019). "Ex vivo activation of NK cells with a naturally occurring HSP70 peptide and IL-2 (TKD-IL-2) enhanced the anti-cancer ability of NK cells against lung cancer and glioblastoma in preclinical tumor models." (PMID 31878360, 2019). "Herein, we aimed to investigate the antitumor effects of a combined therapy consisting of ex vivo Hsp70-peptide TKD/IL-2-activated NK cells in combination with mouse/human anti-PD-1 antibody in a syngeneic glioblastoma and a xenograft lung cancer mouse model." (PMID 30967859, 2019). "In lung cancer patients, IL-2 treatment reverses CD8+ T cells exhaustion and markedly increases Granzyme B and IFN-γ in malignant pleural effusion." (PMID 30619765, 2018). "CIK cells stimulated with a combination of IL-2 and IL-15 have shown greater cytotoxicity against human lung cancer cells." (PMID 29184163, 2017). "The primary tumors in above ten SMUP patients with elevated of IL-2 levels were lung cancer, myeloma, kidney cancer, esophageal cancer, liver cancer or gastric cancer." (PMID 26115010, 2015). "NK1.1+CD3− NK cells activated by IL-2 in vitro have significant cytotoxic activity to high/low metastatic lung cancer large cells." (PMID 25299645, 2014). "More importantly, our findings have indicated that acupoint stimulation upregulates IL-2 in lung cancer patients." (PMID 24344728, 2013). "In the case of MNCs from lung cancer patients, IL-10 production was more prominent when cells were incubated with IL-2 than with IL-15." (PMID 9744501, 1998). "The enzyme-linked immunosorbent assay (ELISA) results revealed that the Tet-HER1-CAR-T cells activated by Doxy and Doxy@CaCO3-PEG in the presence of HER1-overexpressing TNBC (MDA-MB-468) and lung cancer (NCI-H23) cells effectively secreted IL-2, IFN-γ and TNF-α at comparable levels." (PMID 40927437, 2025). "M28z10 CAR-T cells exhibited enhanced and sustained antitumor activity against MSLN+ lung cancer cells in vitro, and the secretion of Interleukin-2 (IL-2), Interferon-γ (IFN-γ), granzyme B and granulocyte–macrophage colony-stimulating factor (GM-CSF) was increased." (PMID 39023820, 2024). "Additionally, research has shown that activating IL‐2 can help restore lymphocyte immunocompetence against lung cancer." (PMID 38647237, 2024). "And IL-2 injection enhanced the function of IRF1 on A549 lung cancer cells." (PMID 38915471, 2024). "It is suggested that the synergistic effect of IRF1 and IL-2 in A549 lung cancer cells in vitro." (PMID 38915471, 2024).
lung carcinoma (continued). "Furthermore, the regression analysis demonstrated that patients with lung cancer had significantly higher odds for increased levels of IL-1b, IL-2, IL-6, and IL-12p70 above the calculated cut-off values." (PMID 37373957, 2023). "Moreover, the ROC plot analysis revealed that several inflammatory markers, including IL-1b, IL-2, IL-6, IL-10, IL-12p70, and TNF-alpha, are significantly associated with the risk of lung cancer." (PMID 37373957, 2023). "Furthermore, TLR2 stimulation induced by a natural polysaccharide in a lung cancer model induces NK cell activation, proliferation, cancer cell-directed cytotoxicity, and the release of IL-2 and IFN-γ." (PMID 36499361, 2022). "Moreover, by promoting the expression of multiple target genes, including DDIAS, cyclin D1, IL-2, and IL-4, NFATc1 protects lung cancer cells against anticancer drug-induced death." (PMID 33859351, 2021). "In addition, it has been proved that IL-2 activation plays an essential role in the restoration of the immunocompetence of lymphocytes against lung cancer." (PMID 32802118, 2020). "In conclusion, this study reveals a subset of NK cells with high expression of PD-1 in the blood of the patients with lung cancer, and the abundant of these PD-1+ NK cells may be related to the increased concentration of IL-2 in the plasma of the patients." (PMID 32788875, 2020). "Importantly, in patients with lung cancer, the percentage of PD-1+ NK cells was significantly positively correlated with the concentration of IL-2 in the plasma, which was also higher than that in healthy individuals." (PMID 32788875, 2020). "Notably, in lung cancer, the concentration of plasma IL-2 was positively related with the proportion of PD-1+ NK cells in the blood." (PMID 32788875, 2020). "In addition to this, it can provide a beneficial effect in anticancer treatment by promoting IL-2, T cell subtypes, and natural killer cells in lung cancer patients." (PMID 27190532, 2016). "To avoid any effect that either IL-2 or culturing may have on the NK cells we further directly isolated lymphocytes from breast, colon and lung carcinomas." (PMID 26079948, 2015). "However, elevated IL-2 levels have previously been reported in cases of solid tumors of lymph node metastasis, including gastric cancer and lung cancer." (PMID 26115010, 2015). "The findings of higher levels of both TGF-β1 and IL-2 suggest that these proinflammatory cytokines might promote the generation and differentiation of Tregs in lung cancer." (PMID 24872958, 2014). "Later, in phase I clinical trial they have shown in patients with metastatic colon carcinoma and nonsmall cell lung cancer that the application of ex vivo TKD/IL-2 activated autologous leukapheresis product is safe and maintained the cytolytic activity against autologous tumors." (PMID 23476104, 2013). "Statistical significance was observed for IL-1b (p = 0.044), IL-2 (p = 0.040), IL-6 (p = 0.001), IL-10 (p = 0.008), IL-12p70 (p = 0.001), and TNF-alpha (p = 0.046), indicating that these inflammatory markers are significantly associated with the risk of lung cancer." (PMID 37373957, 2023). "Propper etal's study 36 indicates that IPCGOR combined with IL-2 significantly improves PFS, OS, and ORR in patients with advanced lung cancer compared to the IPCGOR regimen alone,consistent with this study." (PMID 38434976, 2024). "Activated T cells release macrophage migration inhibitory factor to suppress glucocorticoid-mediated production of IL-2 and IFN-γ, which promotes lung cancer cell proliferation and the Warburg effect." (PMID 39735553, 2024). "The study measured the concentration of IFN-γ, TNF-α, IL-1β, IL-2, IL-4, IL-6, IL-10, and IL-12p70, in venous blood and BALF of a total of 33 patients with lung cancer and 33 patients with benign lung diseases." (PMID 37373987, 2023). "Th1 cells, which release tumor necrosis factor alpha(TNF-α), IL-2, and interferon gamma (IFN-γ), contribute to antitumor immune responses in lung cancer." (PMID 36776832, 2023).